CD4 (CD4 molecule)
Diseases named in the same sentence as CD4 in open-access papers (continued):
Sharing a sentence is not in itself a finding about the gene and the disease.
infection (continued). "In contrast, animals treated with SSO up to 24 h before infection exhibited levels of Ly-6C+ monocytes, Ly-6G+ neutrophils, CD4+ T cells, and CD8+ T cells comparable to those of the PBS-treated control group." (PMID 40137298, 2025). "In the lymphoid compartment, the majority of cell clusters were CD4+ TEM and CD8+ TEM cells in which the CD11c+CD4+ TEM cell cluster (lym-21) was dominant 48 h after infection while the other T-cell clusters were enriched 0–24 h." (PMID 40237529, 2025). "This imprinting, induced in vivo by combo treatment, protected bystander CD4+ T cells from infection by rebounding SIV post ATI." (PMID 40166014, 2025). "After infection resolution, most T cells undergo apoptosis, but a small subset in both CD4+ and CD8+ populations persists as memory T cells, which can respond rapidly to reinfection." (PMID 40867680, 2025). "Human T-cell leukemia virus type 1 (HTLV-1) is a retrovirus that primarily infects CD4+ T cells in vivo, establishing a lifelong infection." (PMID 40004169, 2025). "Compared with Sham-group, 17ZR101-infection resulted in an increased frequency in Tem and exhausted CD4 T cells, but with a decreased naïve population." (PMID 40096073, 2025). "Similar to CD8+ T cells, differentiation fate of CD4+ TM cells is suggested to be determined during the priming phase of infection." (PMID 40391228, 2025). "While 100% productive infection and CD4+ T cell decline was seen with the ADA strain, only 50% infection and no CD4+ T cell decline was noted with the C1157 virus." (PMID 40308596, 2025). "Meanwhile, CD4+ T cells were found to peak around 6–8 days post-infection in the lymph nodes of mice using a genital infection of HSV-1." (PMID 40431612, 2025). "It should therefore not be ruled out that LCM, or even peritoneal macrophages altogether, are dispensable for the antigen‐specific interactions that cause the upregulation of cell‐surface CD154 observed in cavity CD4+ T cells in primary infection." (PMID 41388224, 2025). "In pregnant women, early post-infection CD4+ T cell responses are predominantly directed against gB and pp65." (PMID 41194662, 2025). "Immune activation, in turn, produces an additional number of activated CD4+ T lymphocytes that serve as a target for new infections." (PMID 41415703, 2025). "If the virus encounters CD4 T cells within a few hours, a viral synapse forms with contacting CD4 T cells, allowing transfer to and the infection of the T cells." (PMID 39861894, 2025). "To further investigate CD4+ T cell subset dynamics, we isolated PBMCs at various post-infection time points and quantified distinct subsets by qPCR analysis of T cell-specific transcription factors." (PMID 40742129, 2025). "Within the context of natural infection, several previous studies have already shown significant positive associations between SARS-CoV-2-specific CD4+ T-cell responses and serological antibody levels and neutralization (4, 5, 20, –, 22)." (PMID 39887249, 2025). "A combination of adoptive cell transfer, flow cytometry, histological analysis, and single-cell RNA sequencing (scRNA-seq) was applied to analyze the differentiation of CD4+ T cells into TFH cells at multiple infection stages." (PMID 40777021, 2025). "Infection also triggers expansion of effector memory CD4+ and CD8+ T cells, accompanied by a Th1-skewed cytokine profile characterized by elevated IL-1β, IL-6, IL-8, and TNF." (PMID 41472229, 2025). "In a model of genital tract infection, IFN-γ produced by CD4+ T cells was shown to be critical for controlling infection and preventing tubal disease." (PMID 41156830, 2025). "CXCR3 and CCR6 were used to study the other CD4+ T-helper cell (Th) populations, in relation to the different latency profiles and infection statuses." (PMID 40963636, 2025). "In contrast, CD8+ T cell depletion only enhanced S. aureus titers in the galea at day 7, supporting the importance of CD4+ T cells for infection containment." (PMID 39989461, 2025).
infection (continued). "To further assess the impact of CD4+ T cell depletions on the Ab response, we measured IgG subclasses IgG1 and IgG2 after infection." (PMID 41295476, 2025). "Following the initial proliferative response to primary infection, the CD4+ T cell population contracts, leaving behind long-lived memory cells of Th1, Tfh, central memory (TCM) and effector memory (TEM) phenotypes." (PMID 41194662, 2025). "Specifically, the percentage of PEDV entering CD4+ Tcells reached a peak at 1 hour post-infection (1 hpi) and then graduallydecreased." (PMID 40094365, 2025). "Th1 and Th17 transfer also reduced the frequency of G-MDSC and PMN infiltrates in the brain of Rag1–/– recipients compared with Rag1–/– mice alone, suggesting that CD4+ T cells regulate granulocyte recruitment during craniotomy infection." (PMID 39989461, 2025). "Excluding PWH who had CD4 counts <200 cells/μL generally strengthened the association between HIV-1 viremia and cancer risk, particularly for infection-related cancers." (PMID 39736138, 2025). "Animals were sorted into infusion groups taking into account their age, weight, time post-humanization, peak viral load, viral load area under the curve, and CD4 counts pre-infection." (PMID 41332665, 2025). "We were able to show, that PTCY positively influences lymphocyte reconstitution compared to MM/ATLG, with higher counts of NK, naïve CD4+, CD4+, and B lymphocytes at one year, correlating with a lower late infection burden in the PTCY group." (PMID 39562716, 2025). "As we found for the CD8 T cells, the joint distribution of marker expression on CD4 T cells gradually shifted with time post infection." (PMID 40060443, 2025). "By 4-weeks post-infection and treatment, PbTII cells and polyclonal CD4+ T cells exhibit GC Tfh (PD1hi CXCR5hi), Tfh/TCM-like (CXCR5+ PD1lo) or Th1-TEM (CXCR5lo CXCR6+) memory phenotypes in the spleen." (PMID 40132035, 2025). "In ourexperiments, we observed that PEDV invaded CD4+ T cells within 1 hpost-infection and began transcription approximately 6 h later." (PMID 40094365, 2025). "Here, we established the systemic LCMV Cl-13 infection in gnotobiotic mice and investigated adaptive anti-viral immunity by tracking adoptively transferred virus-specific CD4+ T cells." (PMID 40274773, 2025). "In agreement with our previous data, IFNγ production by CD4+ T cells significantly increased upon infection in both WT and TG mice." (PMID 40746561, 2025). "In K18-hACE2 mice, EG.5.1 infection led to a marked reduction in pulmonary CD4+ and CD8+ T cells at 3 dpi when compared to mock-infected controls." (PMID 41012604, 2025). "A longitudinal study confirmed that a CD4+/CD8+ ratio of ≤1.0 indicates low immune function in patients with infection." (PMID 39781531, 2025). "On day 6 post-infection, the mice were euthanized, and the frequency of lung-resident CD4+ and CD8+ T cells was determined by flow cytometry (FACS)." (PMID 40732672, 2025). "The increased number of circulating CD4+CTLs in supercentenarians indicates the development of unusual characteristics in the circulating lymphocytes to fight against infections and diseases to support their healthy longevity." (PMID 41009359, 2025). "Here, chemically sympathectomised mice exhibited significantly reduced CD4+ T cell recruitment to the infection site upon secondary exposure to S. aureus compared to SNS-sufficient controls." (PMID 41124072, 2025). "Children with ongoing infection presented lower percentages of CD4 T-cells with proliferative potential (CD25+ CD134/OX40+) after PHA stimulation (p = 0.0024)." (PMID 41011738, 2025). "Although Tregs are less permissive to HIV replication than activated CD4+ T cells, they express both CD4 and CCR5, rendering them susceptible to direct infection and apoptosis, particularly during early infection." (PMID 40573430, 2025). "All clones demonstrated the ability to productively infect and replicate within CD4+ T cells for up to 14 days post-infection." (PMID 40284910, 2025).
infection (continued). "This inflammation can contribute to the recruitment of other immune cells to the site of infection, including CD4+ T cells, which are the primary targets for HIV." (PMID 40901106, 2025). "Although antigen-specific effector CD4+ T cells can restrict Mtb bacterial growth, they are insufficient to prevent initial infection establishment." (PMID 40825006, 2025). "Stein A previously reported a case of HIV infection with low CD4 counts complicated by TW infection." (PMID 40708635, 2025). "After resolution of infection with wild-type Leishmania major parasites, the skin of cured mice harbours CD4+ TRM cells that are essential for optimal immunity against Leishmania reinfection." (PMID 41361890, 2025). "CD4+ Th17-like cells have also been associated with robust CD8+ T cell immunity and resolution of infection." (PMID 40956619, 2025). "At day 3 post-infection, medium (160 mg/kg) and high (320 mg/kg) doses of baicalin significantly increased the CD4+/CD8+ T cell ratio compared with the virus-infected model group (P < 0.01)." (PMID 40406095, 2025). "Latent infection of HIV-1 in resting CD4+ T lymphocytes is the major obstacle in virus eradication in PWH receiving cART." (PMID 39692477, 2025). "During the initial infection, the body mounts a robust immune response, characterized by the activation of both CD4+ and CD8+ T cells targeting EBV antigens." (PMID 40732748, 2025). "Seven out of nine of the CD4+ T cell subsets differed by infection status whereas only two out of eight of the CD8+ subsets differed." (PMID 40313463, 2025). "In CCR2WT mice, CD4+ T cell depletion resulted in a 100-fold increase in Mtb bacteria within the lungs at 6 weeks post-infection." (PMID 40489538, 2025). "We observed increased pulmonary CD4+ T cell responses from early time points after infection in C57BL/6 mice compared with C3HeB/FeJ mice that were independent of the infecting M. tuberculosis strain." (PMID 40986319, 2025). "Administration of anti-IL-10 to iron-loaded Tim3−/− animals or to splenocytes ex vivo restored IFNγ expression of CD4+ T cells and improved infection control under high iron conditions." (PMID 40939292, 2025). "Studies on Mtb have indicated that mice infected with Mtb have depleted CD4 T cells, which consequently contributes to widespread infection; however, their presence restricts bacterial proliferation." (PMID 41306590, 2025). "Consistent with our 12-day infection, the CD4 + CTLs decreased, effector memory (EM) T cells increased, and NK cells were unchanged in the 21-day infection." (PMID 40386405, 2025). "In comparison, P. timonensis induced minor maturation of primary LCs but also strongly enhanced uptake and transmission by LCs, while the enhanced uptake in CD4+ T cells leads to enhanced productive infection." (PMID 40071689, 2025). "The immunologic effects of long-term and/or high-dose systemic corticosteroid use include CD4 T-cell lymphopenia and SHG, leading to an increased risk of infection." (PMID 39871382, 2025). "Comparing our results using the Tulahuen strain, infection with Y strain induces a higher frequency of CD4+ T cells with CTL phenotype." (PMID 40590226, 2025). "This approach ultimately activates TCR signalling, leading to increased CD4+ T cell proliferation ex vivo and enhanced protection against infections in murine models." (PMID 40883510, 2025). "Subsequently, we assessed PD-1 expression within AIM+CD4+ T cells based on the history of infections." (PMID 39989460, 2025). "A previous study indicated that the CD4+/CD8+ ratio is an indicator of immune competence in individuals with infection." (PMID 39781531, 2025). "Our study demonstrated that PEDV infection significantlyupregulates integrin α4β7 expression on CD4+ T cells.Inhibiting this integrin effectively prevents the migration of these infectedlymphocytes into the gut, thereby blocking infection." (PMID 40094365, 2025).
infection (continued). "Conversely, females had increased lung CD4 + T cell recruitment after Omicron infection and significantly elevated lung MCP‐1 secretion after Delta infection than males." (PMID 40686017, 2025). "Eradication of latent reservoirs of HIV-1 seeded early in the infection either by the direct infection of resting CD4+ T cells or reversal of infected activated CD4+ T cells into a quiescent state is critical for the cure of HIV-1." (PMID 40168443, 2025). "Early-stage infection showed marked reduction in CD4+ T cell counts, with gradual recovery thereafter." (PMID 40742129, 2025). "We next established a method to test for T-cell intrinsic gene function in Plasmodium-specific TCR transgenic CD4+ T cells during infection, using the transcription factor, Maf, as a test case." (PMID 40132035, 2025). "In contrast, the DNA hypomethylation level in CD4+ T cells gradually increased during the infection." (PMID 40170749, 2025). "This group is in a later phase of the infection, with lower CD4+ T-cells and higher plasma viral loads." (PMID 41120653, 2025). "We observed that both prior to and after infection, 40RD mice displayed reduced numbers of B cells, CD4 T cells, and CD8 T cells compared to controls." (PMID 40662940, 2025). "Co‐transfection resulted in robust p24 production (1100 ng/ml at day 7 post‐transfection) and successful infection of primary CD4+ T cells (9900 ng/ml at day 7 post‐infection)." (PMID 40657994, 2025). "CD4 antibody treatment of macrophages phenocopied the infection-promoting effect of CD4+ T cell coculture." (PMID 40130873, 2025). "This vector promotes more efficient infection of resting CD4+ T cells by allowing complementation with Vpx protein." (PMID 40168443, 2025). "CD38 expression increased in both CD4+ T cells in the cerebrospinal fluid four weeks post-infection, and the chemoattractant IP-10 was elevated at the eighth week." (PMID 40804634, 2025). "Possibly, once endocytosis is impaired, more virions can enter upon fusion at the plasma membrane leading to productive infection as previously seen in CD4+T cells." (PMID 40029073, 2025). "These filopodia contact and capture CD4 T cells, leading to viral synapse formation between them, releasing the budding HIV virions into the synapse for passage to CD4 T cells, leading to their infection." (PMID 40929143, 2025). "In another study, IL2 promoter was found completely methylated in naive CD4+T cells and demethylated in memory CD4+T cells during infection." (PMID 40537863, 2025). "The findings support other studies demonstrating viral RNA in human and NHP CSF CD4+ T cells during acute and early infection, and further implicate CD4+ T cells as potential mediators of HIV-1 entry into the CNS." (PMID 40099824, 2025). "SupT1 cells were infected with NL4–3 or NLRev_IRES_Nef viruses at an MOI of 0.005 and then stained for intracellular p24 and surface CD4 expression at day 8 post-infection." (PMID 40372991, 2025). "Based on previous observations of fusion in reverse, we tested CD4 and CXCR4 variants for their abilities to be assembled into HIV-1-based lentivirus vectors and accomplish fusion in reverse infections." (PMID 40284914, 2025). "While the depleted groups showed minimal inflammation at 4 wk after infection, most CD4- and CD8α-depleted macaques had high lung FDG activity by 8 wk after Mtb, with significantly higher total lung FDG activity compared with IgG/saline-vaccinated animals." (PMID 39912921, 2025). "To understand the influence of Tr1 cells on the systemic response to infection, we quantified the abundance of Tr1-associated molecules (granzyme A, IFNγ, IL-10, and LAG3) in plasma from the same blood samples used to study CD4+ T cells as a part of MUSICAL." (PMID 41000872, 2025). "We also observed significant increases in m6A levels in primary CD4+ T cells upon infection with an R5-tropic HIV-1NLAD8 strain." (PMID 41085277, 2025).
infection (continued). "Diversion of IFN signaling is associated with increased expression of inflammatory markers, enhanced release of inflammatory cytokines, and delayed contraction of infection-induced CD4+ T cells." (PMID 40834853, 2025). "We infected mice with LCMV WE and isolated CD4 T cells at Days 4, 5, 10, 15, 25, and 40 of the infection, which were then stimulated with our cytokine combination to determine their ability to produce IFN‐γ in response to this TCR‐independent stimulation." (PMID 40923840, 2025). "Of the 124 individuals for whom Fiebig stage and CD4+ count were available, 30 had advanced infection (Fiebig stage VI and CD4+ count below 200 cells/mm3), representing 24.2% of new HIV diagnoses made in the ED." (PMID 41289038, 2025). "Early infection with E. granulosus activates innate immunity, but as the metacestode forms, the CD4+T cell-mediated immune response diminishes, allowing E. granulosus to grow." (PMID 40909266, 2025). "PD-1 and ICOS declined on functional HCV-specific CD4+ T cells with control of viremia, as observed in humans with resolving infections." (PMID 40956619, 2025). "CD4+ follicular helper T cells (TFH) play a crucial role in initiating an effective B-cell response during infections by forming germinal centers in secondary lymphoid tissues, which are essential for B-cell maturation, proliferation, and memory development." (PMID 39897040, 2025). "The presentation of microbial molecules to CD4+ T cells is a key component of an effective immune response to infection." (PMID 39886799, 2025). "The initial event to achieve strain replacement must be new infection of a CD4+ T cell that reverts to latency." (PMID 40464563, 2025). "This reactivation not only increases viremia but also facilitates infection of bystander activated CD4+ T cells, perpetuating the viral reservoir." (PMID 41009690, 2025). "This is followed by a latency phase between 1– and 2-weeks post-infection in the CD4+ αβ T-cell subset that results in systemic viral dissemination." (PMID 40733625, 2025). "Functional analysis of Eng2-specific CD4+ T cells in vaccinated C57BL/6 mice following infection with C. posadasii and H. capsulatum." (PMID 41061037, 2025). "In contrast, infection of CoMtb mice induced an increased representation of activated CD4 T cells (primarily defined by CD44 and IFNg) and MDCs at early time points (d17), and this was correlated with decreased bacterial burdens at this time point." (PMID 40736456, 2025). "When the mice were pretreated with 100 mg/kg BW baicalin, the proportions of CD3+ and CD3+CD4+ T cells were upregulated compared with the infection group (p < 0.05)." (PMID 40305201, 2025). "Comprehensive analyses of T‐cell responses showed that SFV + IAV– and SFV‐infected mice had greater brain CD8+ T‐cell infiltration compared with IAV infection at 7 dpi, while SFV‐only infection had more CD4+ T cells in the brain compared with IAV infection." (PMID 39971320, 2025). "A notable example is the infection of CD4+ T lymphocytes by HIV, where the activation of Rac1, Cdc42, and RhoA depends on the membrane localization of the viral protein Gag and its interaction with specific membrane phospholipids." (PMID 40316910, 2025). "In fact, CD11b− DCs, neutrophils, and NK cells also significantly increased during the late phase, and we observed mature granulomas with CD4+ T cell rims surrounding neutrophils and phagocytes only at this late stage of the infection." (PMID 39807873, 2025). "In contrast, mice are able to clear infection in a CD4+ T cell-dependent manner, but an efficient CD8+ T cell response is not generated." (PMID 39772728, 2025). "The key observation is that memory CD4+ T cells tend to accumulate in correlation with each prior infection in the preinapparent group." (PMID 39989460, 2025).